SDHA (succinate dehydrogenase complex flavoprotein subunit A)
Diseases named in the same sentence as SDHA in open-access papers (continued):
Sharing a sentence is not in itself a finding about the gene and the disease.
ovarian carcinoma (continued). "Therefore, we quantified cellular ATP production rates in SDHA-high and SDHA–low ovarian cancer cell lines by performing Seahorse XF Real-Time ATP Rate Assay." (PMID 36291881, 2022). "To study the functional consequences of SDHA upregulation in ovarian cancer, we generated a panel of ovarian cancer cell lines, where we conditionally overexpressed SDHA in SDHA-low cell lines using doxycycline (dox) inducible system, or performed stable SDHA knockdown (KD) in OVSAHO cells." (PMID 36291881, 2022). "Importantly, we showed here that SDHA overexpressing tumor cells can be effectively targetable by anti-metabolic compounds such as shikonin, which represents a new opportunity for therapeutic intervention in ovarian cancer." (PMID 36291881, 2022). "Next, to determine if SDHA or LRPPRC depletion affects each other’s protein expression, we knocked down (KD) either SDHA or LRPPRC in several mouse and human ovarian cancer cell lines." (PMID 40563592, 2025). "Our analysis of transcriptomics data showed that the tumor-specific upregulation of SDHA is accompanied by LRPPRC overexpression, particularly in advanced ovarian cancer." (PMID 40563592, 2025). "Next, we measured SDHA and LRPPRC protein expression in mouse and human ovarian cancer cell lines, HGSOC PDXs, and normal hFTs using WES(ProteinSimple) and observed a concomitant SDHA and LRPPRC protein expression in all examined tissues." (PMID 40563592, 2025). "Specifically, SDHA and LRPPRC expression was significantly lower in normal FT when compared with ovarian cancer." (PMID 40563592, 2025). "Our findings revealed a shift toward significantly higher gene expression of both SDHA and LRPPRC when precursor lesions progressed to advanced ovarian cancer." (PMID 40563592, 2025). "Lastly, we demonstrated that shikonin treatment in vitro leads to a loss of OXPHOS activity, bioenergetic dysfunction, and death of SDHA- and LRPPRC-overexpressing ovarian cancer cell lines." (PMID 40563592, 2025). "In summary, we investigated the unique metabolic features of ovarian cancer and discovered that tumors with a high-OXPHOS phenotype are characterized by the concomitant overexpression of SDHA and LRPPRC." (PMID 40563592, 2025). "This work brings to light, for the first time, a possible functional relationship between SDHA and LRPPRC in the development and progression of ovarian cancer disease." (PMID 40563592, 2025). "Overall, we strive to advance scientific knowledge by highlighting the understudied role of SDHA and LRPPRC in ovarian cancer and their potential utility as biomarkers of high-OXPHOS tumors to guide personalized cancer therapy." (PMID 40563592, 2025). "Our analysis of SDHA and LRPPRC gene and protein expression patterns in precursor lesions and established ovarian cancer demonstrated that the upregulation of SDHA is accompanied by LRPPRC overexpression, notably in advanced tumors." (PMID 40563592, 2025). "Previous studies have reported that under normoxic conditions, the most stably expressed genes in ovarian cancer cells are GAPDH/TBP, while under hypoxic conditions, the most stable candidate housekeeping genes are RPL13A/SDHA." (PMID 38166541, 2024). "In the subset of ovarian cancer cell lines, the reference genes were PPIA, RPS13 and SDHA, clearly demonstrating the necessity to select genes depending on the research focus." (PMID 23554992, 2013). "We made similar observations in various human ovarian cancer cell lines with and without SDHA overexpression or knockdown, where the SDHA upregulation promotes cell proliferation and survival in suspension cultures but not in adherent cell cultures." (PMID 40563592, 2025). "Potent shikonin efficacy in vitro has been previously reported in ovarian cancer with upregulated SDHA; however, there is a lack of respective in vivo data validating shikonin as affecting treatment in these tumors." (PMID 40563592, 2025).
ovarian carcinoma (continued). "Collectively, our in vivo data demonstrated that shikonin treatment results in a durable therapeutic response and can be an effective treatment in preselected SDHA- and LRPPRC-overexpressing ovarian tumors, which introduces hope for improving current therapies for ovarian cancer patients." (PMID 40563592, 2025). "We aimed to determine changes in SDHA and LRPPRC gene expression ranging from early precursor lesions to advanced-stage HGSOC to provide insight into the potential role of those molecules in the development and progression of ovarian cancer disease." (PMID 40563592, 2025). "Therefore, we analyzed GeoMx spatial transcriptomics data to determine the SDHA and LRPPRC expression patterns in human HGSOC samples to provide insight into their potential roles in driving ovarian cancer onset and disease progression." (PMID 40563592, 2025). "We next evaluated SDHA and LRPPRC gene and protein expression patterns in precursor lesions and advanced HGSOC samples and demonstrated that the tumor-specific upregulation of SDHA consistently coincides with LRPPRC overexpression, especially in advanced ovarian cancer." (PMID 40563592, 2025). "First, the presence or absence of immunohistochemically detectable mitochondria was validated in human kidneys and in different clinical samples of ovarian cancers using three monoclonal antibodies directed against different mitochondrial antigens, namely HSP60, fumarase and SDHA." (PMID 38191325, 2024). "Together, these data showed that a reduced supply of glucose or glutamine inhibited mitochondrial respiration to certain degree in ovarian cancer cells with and without SDHA overexpression." (PMID 36291881, 2022). "First, we used pairs of ovarian cancer cell lines with and without SDHA overexpression and recorded basal rates of OCR, ECAR, and PER." (PMID 36291881, 2022). "All cell lines regardless of SDHA status, demonstrated higher rates of ATP production from glycolysis, which suggests that ovarian cancer preferentially uses glycolysis pathway to fulfill the energy requirements." (PMID 36291881, 2022). "Moreover, in the subset of normal and ovarian cancer cell lines, the respective genes were PPIA, RPS13 and SDHA." (PMID 23554992, 2013). "However, the role of SDHA upregulation and its impact on ovarian cancer metabolism has never been investigated, emphasizing the need for further research." (PMID 36291881, 2022). "Our novel findings shed light on an unexplored link between SDHA and LRPPRC in ovarian cancer, and to the best of our knowledge, there are no studies directly investigating a functional relationship between those key metabolic regulators." (PMID 40563592, 2025).
prostate carcinoma (9 papers, 2014 to 2026). A carcinoma that arises from epithelial cells of the prostate gland. "The third case involves a man in his sixties with prostate cancer, found to carry an incidental SDHA variant after undergoing broad cancer predisposition panel testing." (PMID 41635891, 2026). "By contrast, in a recent report analyzing mitochondrial function in prostate cancer, increased SDHA expression was associated with reduced respiratory capacity and a significant metabolic shift towards higher succinate oxidation, particularly in high-grade tumors." (PMID 33916314, 2021). "The first case is a 72-year-old male with a history of prostate cancer and GIST, where genetic testing revealed germline variants in BRCA2 and SDHA." (PMID 41635891, 2026). "He had no personal/family history of SDH-associated tumours, and his prostate cancer showed strong SDHA expression, indicating that the variant was non-actionable, and no surveillance for SDH-associated tumours or familial cascade testing was recommended." (PMID 41635891, 2026). "We show here that high levels of nuclear ARRB1 in prostate cancer cells result in downregulation of FH and SDHA expression, although this effect is likely to be an indirect consequence as our genomics analysis did not identify any ARRB1-binding sites in the promoter regions of these two genes." (PMID 24837709, 2014).
renal cell carcinoma (8 papers, 2013 to 2025). "Succinate dehydrogenase (SDH)-deficient renal cell carcinoma (RCC) is a rare RCC subtype that is caused by biallelic mutation of one of the four subunits of the SDH complex (SDHA, B, C, and D) and results in inactivation of the SDH enzyme." (PMID 29872718, 2018). "Mutations in protein subunits of succinate dehydrogenase (SDHA/SDHB/SDHC/SDHD and assembly factor SDHAF2) and fumarate hydratase (encoded by the single gene FH) lead to rare forms of renal cell carcinoma (RCC; denoted by SDHRCC and FHRCC, respectively)." (PMID 35288096, 2022).
glioma (7 papers, 2018 to 2026). A benign or malignant brain and spinal cord tumor that arises from glial cells (astrocytes, oligodendrocytes, ependymal cells). "The CPGs most frequently affected by GVs were ATM in 6/206 (2.9%) families, BRCA2 in 5/206 (2.4%) families (identified in approaches 1 and 2), GBA1 in 4/206 (1.9%) families as well as EGFR, GJB2, and SDHA in 3/206 (1.5%) families each of the glioma cohort." (PMID 41546701, 2026). "Gliomas from SDHA GV carriers with less DSB accumulation showed a trend towards a higher mean nuclear IRS of RAD51 than those from ATM, BRCA2, and FANCA GV carriers with more DSBs." (PMID 41546701, 2026). "When we used univariate Cox's regression analysis, we found that ASL, ADSL, and FH were unfavorable factors for glioma patients, while SDHA was a favorable prognostic factor for patients." (PMID 37786553, 2023). "The mean nuclear IRS of phospho-H2AX indicating DSB accumulation was lowest in gliomas from SDHA versus ATM, BRCA2, and FANCA GV carriers, although the differences were not statistically significant, possibly because SDHA variants are least directly linked to impaired DSB repair." (PMID 41546701, 2026). "Blood–brain barrier penetrant PARP inhibitors may be effective in glioma patients carrying GVs in ATM, BRCA2, BRIP1, FANCA, and SDHA identified here that are associated with HRR deficiency, and may act synergistically with radio-, chemo-, and immunotherapy." (PMID 41546701, 2026). "Besides, we also found that ASL, ADSL, and FH promote the malignant phenotype in glioma patients, while SDHA inhibits malignant progression." (PMID 37786553, 2023). "Immune-related pathways such as TNF signalling (IDH3B/G, MDH1, ACO2, SDHA, OGDHL) and JAK/STAT3 (PIAS2/3, PTPN2, AKT1/2, MCL1, CISH, AOX1) signalling are enriched in gliomas and play a critical role in their progression." (PMID 41007296, 2025). "The DICER1 and most of the SDHA and CFTR GV carriers developed glioma after the age of 65 years." (PMID 41546701, 2026). "Collectively, ATF3-regulated SDHA expression could be repressed by EPIC, resulting in mitochondrial respiration disruption and altered metabolic responses in glioma cells." (PMID 36276638, 2022).
hepatocellular carcinoma (7 papers, 2008 to 2026). A malignant tumor that arises from hepatocytes. "However, it is noteworthy that SDHA can also function as a tumor suppressor, as it was frequently found to be decreased in 56% of patients with hepatocellular carcinoma (HCC) tissues." (PMID 40119440, 2025).
Parkinson disease (7 papers, 2018 to 2025). A progressive degenerative disorder of the central nervous system characterized by loss of dopamine producing neurons in the substantia nigra and the presence of Lewy bodies in the substantia nigra and locus coeruleus. "Notably, in Parkinson's disease (PD), the deacetylation of succinate dehydrogenase complex, subunit A (SDHA), mediated by SIRT3, activates mitochondrial complex II, suggesting a critical role for the SIRT3-SDHA axis in promoting metabolic efficacy and neuroprotection." (PMID 38745725, 2024). "A focused subset of Parkinsonism-related proteins—such as DJ-1 (PARK7), succinate dehydrogenase (SDHA), and multiple 26S proteasome subunits—exhibited coordinated dysregulation, as visualized through protein–protein interaction mapping." (PMID 40725009, 2025). "Moreover, Parkinson’s disease (NDUFA9, TUBB4B, etc.; p-value = 4.94E-21), Prion disease (UQCR10, SDHA, etc.; p-value = 4.82E-17) and Pathways of neurodegeneration - multiple diseases (UBA52, etc.; p-value = 6.44E-16) were linked to the low abundant proteins in HF." (PMID 36891514, 2023).
melanoma (6 papers, 2011 to 2025). A malignant, usually aggressive tumor composed of atypical, neoplastic melanocytes. "Western blot analysis combined with measured relative band intensity, normalized against succinate dehydrogenase (SDHA), showed >2 to 4-fold higher Dicer levels in melanoma cell lines (WM278, WM1552C and A375P) when compared to melanocyte-L or other melanoma cell lines (WM35 and A375M)." (PMID 21698147, 2011). "In A375 human melanoma cells (which do not appear to express p16 constitutively), forced expression of p16 resulted in marked downregulation of ND4, SDHA and UQCRC2, while the reduction in PRC and TFAM was less striking." (PMID 28915557, 2017).
glioblastoma (5 papers, 2019 to 2026). The most malignant astrocytic tumor (WHO grade IV). "Patients with GVs in SDHA (n = 3) or TRMT5 (n = 4) were exclusively affected by glioblastoma, IDH-wildtype." (PMID 41546701, 2026). "Collectively, our findings suggested that the PIKE-A/STAT3/FTO/SDHA axis is a promising target for anti-glioblastoma therapy." (PMID 36232604, 2022). "In conclusion, the PIKE-A/STAT3/FTO/SDHA pathway might play a pivotal role in glioblastoma conformation, progression, and proliferation." (PMID 36232604, 2022). "In the present study, we found that exogenous of STAT3 in PIKE-A knockdown glioblastoma cells could rescue the decreased SDHA expression." (PMID 36232604, 2022). "Taken together, the present study reveals a novel mechanism by which PIKE-A promotes tumor growth and demonstrates that PIKE-A regulates SDHA expression by promoting the STAT3/FTO axis, thereby promoting mitochondrial function and cell proliferation in glioblastoma." (PMID 36232604, 2022). "However, the role of SDHA in glioblastoma progression have not been well determined." (PMID 36232604, 2022).
Ataxia (4 papers, 2012 to 2021). Ataxia refers to impaired coordination of voluntary muscle movement. "The possibility of mitochondrial disease should, therefore, be considered in a child presenting with ataxia, intellectual disability, and/or developmental delay and we encourage physicians to consider SDHA mutations in their differential diagnosis." (PMID 33960148, 2021). "Other mutations of SDH subunits that have been implicated in neurodegenerative diseases include SDHA causing ataxia and SDHA, SDHB, SDHD, and SDHAF1 leading to leukodystrophy, yet these studies have been limited to few patients." (PMID 33153035, 2020).
clear cell renal cell carcinoma (4 papers, 2021 to 2025). "According to the previous reporter, SDHA was upregulated in non-small-cell lung cancer with metabolic disorders, which were also found in highly metastatic uveal melanoma and clear cell renal cell carcinoma." (PMID 40186663, 2025). "SIRT5-mediated desuccinylation of SDHA promotes renal clear cell carcinoma tumorigenesis." (PMID 36232604, 2022). "SIRT5-mediated SDHA desuccinylation promotes clear cell renal cell carcinoma tumorigenesis." (PMID 34194607, 2021). "SIRT5 desuccinylates the K547 site of succinate dehydrogenase complex flavoprotein subunit A (SDHA), downregulates its activity and inhibits the binding of SDH5, promoting the development of clear cell renal cell carcinoma (ccRCC) occurrence and progress." (PMID 39979670, 2025).
dilated cardiomyopathy (4 papers, 2012 to 2025). Cardiomyopathy which is characterized by dilation and contractile dysfunction of the left and right ventricles. "Interestingly, genes coding for mitochondrial proteins, such as TAZ, DNAJC19, or SDHA, were responsible for dilated cardiomyopathy." (PMID 40806260, 2025).
multiple myeloma (4 papers, 2020 to 2025). "Different study showed that a high expression of SDHA inhibited cell proliferation and invasion of multiple myeloma cell lines in vitro." (PMID 36291881, 2022).
osteosarcoma (4 papers, 2015 to 2025). A usually aggressive malignant bone-forming mesenchymal neoplasm, predominantly affecting adolescents and young adults. "We have previously found that the amount of mitochondrial translation products, the p.MT-CO1/succinate dehydrogenase complex subunit A (SDHA) ratio and the CIV/CS ratio were significantly lower after treatment with LIN in osteosarcoma 143B cybrids harboring the mtDNA m.3010A allele." (PMID 26398948, 2015).
uveal melanoma (4 papers, 2022 to 2025). A melanoma derived from melanocytes of the uveal tract. "In metastatic uveal melanoma, elevated SDHA contributes to a metabolic dysregulation with increased mitochondrial respiration, which leads to resistance to therapy, and a significantly shorter time to metastasis and death of patients." (PMID 36291881, 2022).
Alzheimer disease (3 papers, 2018 to 2025). A progressive, neurodegenerative disease characterized by loss of function and death of nerve cells in several areas of the brain leading to loss of cognitive function such as memory and language. "Consequently, these two genes were excluded, leaving six critical genes with diagnostic significance for Alzheimer’s disease (AD): ACO2, CS, MRPS27, SDHA, SLC25A20, and SYNJ2BP." (PMID 39757625, 2025).
carcinoids (3 papers, 2017 to 2024). "Michele Simbolo and colleagues’ work on carcinoids reveals differential gene expression, with atypical carcinoids (AC) showing increases in genes such as TERT and SDHA, and typical carcinoids (TC) showing a loss in MEN1." (PMID 38539512, 2024). "There were fewer CNAs in carcinoids than in carcinomas; however ACs showed a hybrid pattern, whereby gains of TERT, SDHA, RICTOR, PIK3CA, MYCL and SRC were found at rates similar to those in carcinomas, whereas the MEN1 loss rate mirrored that of TCs." (PMID 27873319, 2017).
colon adenocarcinoma (3 papers, 2008 to 2026). "Normalization against PPIA/RPLP0/SDHA was found optimal for studies involving various colon adenocarcinoma cell lines subjected to manipulations of serum availability." (PMID 27339468, 2016). "Interestingly, even the isogenic cell lines SW480 (primary colon adenocarcinoma) and SW620 (its lymph node metastasis) significantly differed by SDHA and GUSB expression." (PMID 27339468, 2016).
hereditary cancer (3 papers, 2005 to 2021). Malignant neoplasms occurring in families at a rate greater than that expected by chance and caused by germline mutations in a specific gene. "Other segdup regions, including NEB (exons 83–103), PMS2 (exons 12–15), PRSS1, and SDHA, accounted for 358 additional findings within the hereditary cancer, neurology, and pediatric indications." (PMID 34007000, 2021). "Additionally, SDHA and SDHB variants have been associated with both mitochondrial complex II deficiency in biallelic form, and hereditary cancer susceptibility in monoallelic form." (PMID 34012134, 2021).
ischemia (3 papers, 2022 to 2025). A hypoperfusion of the BLOOD through an organ or tissue caused by a PATHOLOGIC CONSTRICTION or obstruction of its BLOOD VESSELS, or an absence of BLOOD CIRCULATION. "It enhanced SIRT5-mediated SDHα desuccinylation and the GSH/GSSG ratio, while reducing SDHA activity, thereby mitigating succinate accumulation during ischemia and decreasing succinate consumption during reperfusion." (PMID 41260100, 2025). "The link between ischemia and ROS production became even more clear by the finding that the acetylation of SDHA in ischemia leads to the oxidation of succinate, which contributes to ROS production in reperfusion." (PMID 35562962, 2022).